KRAS (KRas proto-oncogene, GTPase)
Diseases named in the same sentence as KRAS in open-access papers (continued):
Sharing a sentence is not in itself a finding about the gene and the disease.
colorectal adenocarcinoma (continued). "Similarly, GSEA of an adagrasib-resistant SW837 (KRAS-G12C mutant colorectal adenocarcinoma cell line) CDX model also suggested that MYC targets were among top enriched pathways compared to treatment naïve tumors." (PMID 40316534, 2025). "Interestingly, oncogenic KRAS-driven stress granules were previously identified in pancreatic and colorectal adenocarcinoma; thus, our result suggests a similar stress response in NSCLC cells." (PMID 35205126, 2022). "In case of absence of a variant in a gene that confers resistance to therapy, it is also important that this absence is clearly mentioned, e.g., no KRAS variant in colorectal adenocarcinoma." (PMID 31888289, 2019). "The aim of this pilot study was to explore intrapatient mixed metabolic response and early 18F-FDG PET response evaluation using predefined quantification strategies in patients with advanced KRAS wild-type colorectal adenocarcinoma (mCRC) treated with cetuximab." (PMID 27196139, 2016). "Thus, our objective was to assess the validity of KRAS and BRAF immunodetection of mutations compared with the genotyping reference method in colorectal adenocarcinoma." (PMID 25983749, 2015). "Clinical activity of sotorasib and adagrasib is unprecedented given that patients with KRAS mutant lung or colorectal adenocarcinomas had no or only limited access to targeted therapies as KRAS mutation is a negative predictive factor for all anti-EGFR therapies." (PMID 38278976, 2024). "Significant inverse correlations between DDX6 and KRAS, 4E-T and KRAS, and DDX6 and NRAS were also observed in colorectal adenocarcinoma (COAD) cell lines." (PMID 37370689, 2023). "After checking the capability of KRAS antibody for immunoprecipitation, we examined the cellular interaction of endogenous KRAS and DX2 in colorectal adenocarcinoma DLD-1 cells and observed that the binding of the two proteins was enhanced by EGF treatment." (PMID 35546148, 2022). "Frequent genetic mutations found in colorectal adenocarcinoma are not exhibited by GCA, which are usually negative for BRAF, KRAS and SMAD4." (PMID 40729214, 2024). "Hence, we used a KRAS- and SMAD4-wild-type colorectal adenocarcinoma cell line, SW48, and its genetically engineered derivative carrying the activating KRASG12D allele." (PMID 35008475, 2021). "It is well known that EGFR and KRAS gene mutations act as positive and negative predictors, respectively, of therapeutic response to EGFR targeted therapies in colorectal adenocarcinoma." (PMID 24782938, 2014).
colorectal adenocarcinoma (continued). "Given that KRAS and BRAF are part of the RAS-RAF-MAPK signaling pathway frequently altered in colorectal adenocarcinoma, these findings support the hypothesis that NECs and adenocarcinoma components may be clonally related and originate from a common precursor cell." (PMID 41153242, 2025). "Multiple authors reported no Epidermal growth factor receptor, BRAF, KRAS, or Adenomatous polyposis coli (APC) mutations in GCA, suggesting that its molecular pathogenesis is significantly different from that of colorectal adenocarcinoma, although again this was not a unanimous finding." (PMID 35903705, 2022).
glioma (119 papers, 2007 to 2026). A benign or malignant brain and spinal cord tumor that arises from glial cells (astrocytes, oligodendrocytes, ependymal cells). "As a result, due to its broad activity, resistance-evasion capacity, and brain penetration, NST-628 shows promise for treating a wide range of RAS- and RAF-driven CNS cancers, including those with KRAS, NRAS, or BRAF mutations." (PMID 41514664, 2026). "Among the resulting gene sets, the presence of two categories related to KRAS signaling was interesting since this signaling plays a crucial role in glioblastoma, even if mutations in the KRAS gene are rare in human gliomas." (PMID 40498028, 2025). "For example, RAS mutations were observed in two glioma subtypes; in grade 2 oligodendrogliomas, KRAS mutations occurred in 4% of cases, while in GBM, they were present in approximately 1%." (PMID 40362343, 2025). "One study highlighted that individuals with KRAS rs7212175 G > A polymorphism genotype have higher susceptibility to developing gliomas." (PMID 40362343, 2025). "This study examined the dependence of gliomas on continuous KRas signalling in the context of Ink4a/Arf deficiency." (PMID 39324445, 2024). "Primary glioblastomas (GBMs) are often associated with disturbed RAS signaling, although mutations in KRAS gene are rare in human gliomas and particularly rare in WHO grade III and IV gliomas in adult patients." (PMID 38225605, 2024). "Our analysis showed that KRAS mutation was a broad risk factor causing multiple dysfunctions in glioma patients." (PMID 38315329, 2024). "KRAS is the undisputed champion of oncogenes, and despite its prominent role in oncogenesis as mutated gene, KRAS mutation appears infrequent in gliomas." (PMID 38225605, 2024). "The study identified eight co-downregulated miRNAs, three co-upregulated miRNAs, and seven genes associated with overall glioma survival, namely, KRAS, IFNB1, ALCAM, ERBB2, STAT3, FOSL1, and EN2." (PMID 36061185, 2022). "RAS mutations were identified in four gliomas with three KRAS mutations and one NRAS mutation in one anaplastic oligodendroglioma, two anaplastic astrocytomas (IDH wild-type in each), and one ganglioglioma." (PMID 34525976, 2021). "In line with this, a work using a glioma model driven by oncogenic KRAS observed that autophagy inhibition using KRAS:shAtg7 cells predisposes cell to senescence, characterized by β-galactosidase activity and SASP markers." (PMID 33324568, 2020). "Makino and colleagues detected four RAS mutations in gliomas: three in KRAS and one in NRAS." (PMID 40362343, 2025). "Glioma patients with KRAS mutations can benefit from treatment with KRAS (G12C) inhibitors." (PMID 38817361, 2024). "KRAS gene polymorphisms are associated with the risk of glioma." (PMID 35832194, 2022). "Indeed, several mouse models of glioma have causally implicated activated HRas and KRas in glioma formation." (PMID 18985151, 2008). "Mutations in genes including ROS1, ALK, NF1, KRAS, MEK, and CRAF have been identified across glioma subtypes, highlighting the necessity for molecular classification beyond traditional histopathology." (PMID 41514664, 2026). "Nevertheless, gliomas are considered KRAS-driven cancers due to its essential role in mouse malignant gliomagenesis." (PMID 38225605, 2024).
glioma (continued). "let-7 miRNA is involved in the malignant behaviour in vitro—proliferation, migration and invasion—of gliomas and stem-like glioma cells as well as in vivo models of glioblastoma multiforme (GBM) via KRAS inhibition." (PMID 38637419, 2024). "KRAS alteration is identified as an oncogene for GBMs, and its over-expression has a crucial role in glioma cell growth and proliferation." (PMID 37483487, 2023). "Mutations in KRAS, HRAS and NRAS are known in gliomas and are often concomitant with BRAF mutations and fusions." (PMID 37490467, 2023). "miR-181d is a potential tumor suppressor in glioma that regulates important target genes involved in carcinogenesis, such as KRAS and BCL2, and is involved in lymph node metastasis in oral squamous cell carcinoma." (PMID 37372400, 2023). "Next, GSEA was performed and the results showed that the KEGG “Glioma”, “Long term potentiation”, and “JAK-STAT signaling pathway”, and the Hallmark “KRAS signaling up”, “UV response up” and “Myogenesis” were the most enriched in high HhS patients." (PMID 37069207, 2023). "Glioma, retinoblastoma, osteosarcoma, bladder cancer, prostate cancer and esophageal cancer are other types of cancers in which the interaction between KRAS and non-coding RNAs has been verified." (PMID 35139853, 2022). "RPTOR amplification was found to be significantly associated with young adult BRCA (FDR = 0.020), while amplifications of KDM5A, CCND2, KRAS, and ARRDC1 were each suggestively associated with young adult gliomas (FDR ≤ 0.148)." (PMID 34788626, 2021). "In young adult gliomas, we identified enrichment of KRAS and CCND2 amplifications with potential targeted treatment options, whereas later-onset LGG showed higher rates of actionable EGFR amplification." (PMID 34788626, 2021). "The role of miR‐134 in gliomas has also been identified; it is reported that miR‐134 inhibited the proliferation and invasion of glioma cells by targeting KRAS and activating the ERK pathway." (PMID 32916774, 2020). "Though, in human glioma cells, Kirsten rat sarcoma viral oncogene homolog (KRAS) has been identified as direct miR-126 target, indicating negative regulation of the ERK pathway." (PMID 30081513, 2018). "It has been reported that miR-181d is downregulated in glioma and acts as a tumor suppressor by targeting KRas and Bcl-240." (PMID 29449544, 2018). "Glioma-associated DEGs AKT2, CCL3, STAT2, VEGFC were up-regulated and HIF1A, KRAS, RET, TGFB2 were down-regulated specifically in the dogs." (PMID 29352201, 2018). "Although the role of miR-181d in metastasis is unclear, a previous report has indicated that it acts as a tumor suppressor in glioma by targeting KRAS." (PMID 27380024, 2016). "Then, because single c-Myc and Cdc20 genes are not sufficient to induce glioma in both CDKN2A+/+ and CDKN2A−/− Ntv-a mice, we explored the role of c-Myc and Cdc20 in glioma development in a RCAS/Ntv-a mouse model using the combination of kRas and Akt3." (PMID 26993778, 2016). "By activating these pathways, several mouse glioma models have been generated, primarily through overexpression of oncogenic KRAS." (PMID 25644510, 2015). "With the recent progress of molecular analysis, KRAS G12R, BRAF V600E mutation, and KIAA1549::BRAF fusion were identified in TG, and the DNA methylation profile of TG suggests its classification as a distinct entity from other lower grade glioma (LrGG)s." (PMID 39432011, 2025).
glioma (continued). "This includes a case of angiomatoid fibrous histiocytoma with EWSR1-CREM fusion, an angiocentric glioma with MYB-QKI fusion, a glioma with MYCN amplification, two patients with non-canonical IDH mutations (both with IDH1 R132S), and a patient with a KRAS mutation." (PMID 38764578, 2024). "Additionally, GJC1 was negatively correlated with hallmark_kras_signaling_dn, which indicated a potential mechanism for suppressing KRAS signaling in glioma, possibly contributing to tumor suppression or influencing therapeutic response." (PMID 39360264, 2024). "The KRAS pathway can be directly targeted and is considered a proto‐oncogene in glioma." (PMID 38332637, 2024). "In our data, the relative level of KRAS mRNA changed in different directions in glioma cell lines." (PMID 36231068, 2022). "KRAS overexpression promoted glioma proliferation and invasion." (PMID 36185204, 2022). "In case 32, the histology was suggestive of angiocentric glioma but showed KRAS G12D." (PMID 36290809, 2022). "let-7b has suspected tumor suppressor function in gliomas and low expression of the let-7 family members may be responsible for the poor prognosis of brain tumors patients through disturbed inhibition of KRAS, HMGA2 and MYC oncogenes." (PMID 31170943, 2019). "miR-126 inhibit the cell proliferation and invasion by targeting KRAS mRNA 3’UTR in glioma cells." (PMID 30691465, 2019). "Therefore, we built a glioma mouse model by combining kRas and Akt family genes in the RCAS/Ntv-a glia-specific mouse model." (PMID 26993778, 2016). "Notably, the induction of tumors by KRas+Akt in Arf−/− mice has been shown to generate predominantly GBM-like gliomas." (PMID 21949886, 2011). "Interestingly, mutations in PIK3CA and KRAS were shown to lead to increased aggressiveness in gliomas and tumor progression independent of IDH mutational status." (PMID 40362343, 2025). "Based on the estimated incidence rates of different pediatric tumors in the US and prevalence of KRAS alterations observed in our cohort, we estimate the highest incidence of KRAS altered cases to be in acute leukemia (n = 553), followed by colorectal (n = 88), ovary (n = 71), and glioma (n = 64)." (PMID 36494601, 2022). "Interestingly, glioma induction with the kRas and Akt3 combination required CDKN2A deletion." (PMID 26993778, 2016). "In another study, overexpressed let-7a inhibited glioma cell malignancy by directly targeting KRAS independently of PTEN, and let-7b in turn inhibits malignant behaviour (proliferation, migration and invasion) of glioma cells and stem-like glioma cells." (PMID 38637419, 2024). "None harbored alterations within genes of the MAP kinase signaling pathway (e.g., BRAF, KRAS, NF1, and PTPN11) that are also common in pediatric gliomas." (PMID 36437415, 2023). "The KRAS gene, which is part of the RAS gene family, is tied with glioma development and progression." (PMID 36776374, 2022). "In vitro, over-expression of miR126 suppresses glioma cell proliferation and invasion via regulation of ERK (extracellular signal-regulated kinase) and KRAS (Kirsten rat sarcoma viral oncogene)." (PMID 30597867, 2018).
glioma (continued). "In all tumour types studied, except glioma, ARG2 and OTC ranked gene lists significantly correlated with KRAS signaling." (PMID 28969007, 2017). "The 8 low-grade gliomas harbored alterations in BRAF, KRAS, FGFR3, and MN1." (PMID 40980447, 2025). "Given the frequent dysmorphic ganglion cells, the low IDH R132H AF, and the presence of KRAS mutation, the integrated diagnosis was considered ganglioglioma rather than IDH-mutant glioma." (PMID 36290809, 2022). "Our enrichment plots data suggest that PYGL may induce glioma proliferation through up-regulation of mTORC1 signaling, PI3K/AKT/mTOR signaling, KRAS signaling up, and angiogenesis pathway." (PMID 34177761, 2021). "In this study, we found that the mutant genes in the metastatic brain tumors included ALK, MDM2, ATM, BRCA1, FGFR1, and KRAS, and there were no glioma-related mutant genes (MGMT, IDH1, IDH2, 1p/19q, BRAF, and TERT)." (PMID 32973641, 2020). "Furthermore, a glioma mouse model obtained by transferring the activated forms of BRAF V600E, KRAS and AKT to neural progenitor cells in Ink4a/Arflox/lox mice has been reported." (PMID 31345255, 2019). "This may hint at a link between CIMP CRC tumors, which are typically associated with BRAF and KRAS mutations but not IDH1 or TET mutations, and CIMP gliomas, which are associated with IDH1 mutations but not BRAF or KRAS mutations." (PMID 27879658, 2016). "Indeed, we found six and ten significant pathways in LGG (Brain Lower Grade Glioma) and UCEC (Uterine Corpus Endometrial Carcinoma) (adj P (Cox) < 0.05) respectively, invariably involvingPIK3CA along with different combinations of other oncogenes (e.g.NRAS,KRAS) interfaces." (PMID 36569594, 2021). "Additionally, important to note is that KRAS and BRAF do not typically co-occur in gliomas, but a common finding in GBM is aberrant RAS signaling." (PMID 37231247, 2023).